STC1 (stanniocalcin 1)
Diseases named in the same sentence as STC1 in open-access papers (continued):
Sharing a sentence is not in itself a finding about the gene and the disease.
ovarian carcinoma (continued). "Autoantibodies against leucine repeat death domain-containing protein (LRDD), stanniocalcin-1 (STC1), and forkhead box a1 (FOXA1) were over-expressed in ovarian cancer patients compared to normal controls and showed an AUC of 0.91, 0.88 and 0.82, respectively." (PMID 38275400, 2024). "By detecting the levels of EMT markers fibronectin, vimentin and slug, it was found that human recombinant STC1 (rhSTC1) promoted EMT thus triggering the proliferation and metastasis of ovarian cancer cells via Akt phosphorylation." (PMID 39654892, 2024). "Both STC1 and STC2 promote epithelial to mesenchymal transition in hypoxic ovarian cancer cells and contribute to their invasion and metastasis as well." (PMID 34867818, 2021). "HIF-1α has also been found to directly induce expression of the STC1 gene, producing STC in human ovarian cancer cell lines." (PMID 34867818, 2021). "STC1 could promote metastasis, lipid metabolism and cisplatin chemoresistance via directly binding to ITGB6 in ovarian cancer." (PMID 36816947, 2023). "Increased STC1 expression was mostly detected in human tumor samples of colorectal cancers and hepatocellular carcinomas (HCC), non-small cell lung cancer, ovarian cancer, breast carcinoma and leukemia." (PMID 29467934, 2018). "Abnormal expression of STC1 protein can be seen in many tissues, and it has been proved that ovarian cancer tissues express STC1 at a lower level compared to nearby normal tissues; However, liver cancer tissues express STC1 in up-regulated manner compared with that of near cancer." (PMID 37287492, 2021). "Healthy ovaries express both STC1 and STC2, and levels are increased in ovarian cancer compared to non-cancerous tissue." (PMID 38396692, 2024).
colorectal cancer (30 papers, 2012 to 2026). A primary or metastatic malignant neoplasm that affects the colon or rectum. "In this study, we aim to explore the genetic landscape associated with colorectal cancer recurrence, with a particular focus on the role of STC1." (PMID 39668832, 2024). "We found that high expression of STC1 was associated with poor overall survival in patients with colorectal carcinoma." (PMID 38036953, 2023). "In an orthotopic mouse model of colorectal cancer, cells from tumors formed in the presence of STC1-deficient fibroblasts displayed reduced intravasation, resulting in fewer and smaller distant metastases." (PMID 25740019, 2015). "Other research has identified STC1 as a mediator of metastasis associated with PDGF receptor function in the colorectal cancer setting." (PMID 25740019, 2015). "In fact, use of the STC-1 expression level as a diagnostic or prognostic biomarker in the blood has been validated in breast, lung, colorectal cancer, as well as hepatocellular carcinoma and leukemia." (PMID 22537917, 2012). "Furthermore, tumors formed in the presence of stanniocalcin-1 deficient fibroblasts demonstrated fewer and smaller distant metastases in an orthotopic mouse model of colorectal cancer." (PMID 34336660, 2021). "Notably, among these genes, STC1 had the highest positive coefficient (0.643), indicating it was the most significant contributor to the model and suggesting a strong association with colorectal cancer recurrence." (PMID 39668832, 2024). "Therefore, STC1 expression by endothelial cells during hypoxia might promote a molecular network regulating cancer-associated fibroblast–tumor cell interactions, leading to colorectal cancer survival and progression." (PMID 39807836, 2025). "TNFAIP3 suppressed STC1 phosphorylation at Thr86 by GSK3β to alleviate STC1 protein degradation, which promoted immune evasion in colorectal cancer." (PMID 40469292, 2025). "We took advantage of a previously reported single-cell atlas of colorectal cancer liver metastases to investigate the pattern of STC1 expression." (PMID 39807836, 2025). "Secondly, although we demonstrated the effects of STC1 knockdown in vitro and in zebrafish models, further investigations using mammalian models are necessary to fully elucidate its role in colorectal cancer progression." (PMID 39668832, 2024). "In colorectal cancer, recent research has shown that STC1 can enhance immune evasion and inhibit immune recognition." (PMID 39668832, 2024). "By upregulating PD-L1 expression, STC1 aids colorectal cancer cells in escaping immune system attacks, thereby facilitating tumor growth and progression." (PMID 39668832, 2024). "Consistent results were observed in DLD1 colorectal cancer cells, where STC1 knockdown led to notable inhibition of cell proliferation, migration, and invasion." (PMID 39668832, 2024). "Future studies should aim to address these limitations and explore the potential of STC1 as a therapeutic target in colorectal cancer." (PMID 39668832, 2024). "The identification of STC1 as a crucial player in colorectal cancer progression opens new avenues for targeted therapies." (PMID 39668832, 2024). "Initially, we analyzed the expression levels of STC1 (Stanniocalcin 1) in colorectal cancer tissues." (PMID 39668832, 2024). "To elucidate the impact of STC1 on colorectal cancer cell functionality, we performed gene knockdown experiments in HCT-116 cells." (PMID 39668832, 2024). "STC1 protein can be secreted by tumor-associated fibroblasts stimulated by PDGF to facilitate the growth and metastasis of colorectal cancer cells." (PMID 37400459, 2023). "Taken together, PDGF‐stimulated fibroblasts increase the migration and invasion of colorectal cancer cells in an STC1‐dependent manner." (PMID 32468698, 2020). "Following an orthotopic mouse model of colorectal cancer, the stroma cells required stanniocalcin-1 (STC1), a PDGF regulator, to promote intravasation of adjacent tumor cells." (PMID 26828526, 2016).
colorectal cancer (continued). "PDGF-stimulated fibroblasts secrete stanniocalcin-1 and stimulate invasion of colorectal cancer cells through upregulation of VIM." (PMID 26954362, 2016). "Yet the pro-apoptotic effects of STC1 were demonstrated in cultured chondrocytes, oxidative stress-induced human nasopharyngeal cancer cells, trichostatin A treated human colorectal cancer cells and in oxidative stressed mouse embryo fibroblasts." (PMID 26469082, 2015). "PDGF-stimulated fibroblasts were shown to increase the migration and invasion of co-cultured colorectal cancer cells in an STC1-dependent manner." (PMID 25740019, 2015). "The observation is dissimilar to other type of cancer cases (i.e. human esophageal squamous cell carcinoma, colorectal carcinoma, and leukemia), in which STC1 was recognized as an unfavorable prognostic factor for post-operative outcome in patients." (PMID 26469082, 2015). "Other studies have associated increased STC1 levels with a possible prognostic role in colorectal cancer based on mRNA levels in the tumor but not plasma protein levels in a randomized setting." (PMID 39807836, 2025). "We hypothesized that STC1 expression reflected the presence of a complex colorectal cancer microenvironment in which cross-talk between angiogenesis-related signaling and stromal activation operates." (PMID 39807836, 2025). "Additionally, analyses of STC1 protein expression from the THPA database indicated that STC1 protein levels were significantly higher in colorectal cancer tissues compared to adjacent normal tissues." (PMID 39668832, 2024). "Support for this concept, and some mechanistic details, was added in a study showing that PDGF-BB-stimulated fibroblasts enhance the migratory and invasive capacities of colorectal cancer cells in a manner involving secretion of PDGF-induced Stanniocalcin-1 (STC1)." (PMID 38980580, 2024). "However, detailed insights into STC1's impact on the functional behavior of colorectal cancer cells remain unexplored." (PMID 39668832, 2024). "In a study of colorectal cancer, it was found that STC1 could be secreted by CAFs and promote cancer metastasis." (PMID 37004088, 2023). "ANGTL4, MMP13 and STC1 secretion by CAFs promotes metastasis of colorectal cancer." (PMID 37254126, 2023). "Besides, stanniocalcin-1 (STC1), which is secreted by CAFs, is recognized as a mediator of colorectal cancer growth and metastasis." (PMID 33391518, 2021). "Furthermore, investigating the functional roles of genes in our signature, particularly STC1, may lead to new therapeutic approaches for preventing and managing colorectal cancer recurrence." (PMID 39668832, 2024). "We previously reported a tendency for STC1 mRNA overexpression in hepatocellular carcinoma (HCC) and colorectal cancer compared with background cancer-free tissues, and also that STC1 mRNA might be a useful molecular marker for the detection of cancer cells in blood of patients with HCC." (PMID 22200953, 2012). "While our study provides valuable insights into the role of STC1 and the RRGS model in colorectal cancer recurrence, several limitations should be acknowledged." (PMID 39668832, 2024). "Our comprehensive investigation of STC1, a key component of the RRGS, provides compelling evidence of its significant role in colorectal cancer progression." (PMID 39668832, 2024). "As a correlation between STC1 and ANG2 levels has been previously demonstrated and both are expressed in endothelial cells, we next decided to investigate their prognostic potential in patients with colorectal cancer." (PMID 39807836, 2025). "This analysis showed that STC1 expression is mainly located within endothelial cells, suggesting that STC1 production is more related to endothelial cell activation in advanced colorectal cancer disease rather than to the number of tumor cells." (PMID 39807836, 2025).
colorectal cancer (continued). "By analyzing differentially expressed genes in recurrent versus non-recurrent colorectal cancer tissues, we seek to investigate the contribution of STC1 to cancer progression and its potential as a prognostic indicator and therapeutic target." (PMID 39668832, 2024). "However, the potential clinical interest of STC1 in colorectal cancer has never been investigated until now." (PMID 39807836, 2025).
hepatocellular carcinoma (17 papers, 2012 to 2025). A malignant tumor that arises from hepatocytes. "STC1 expression is a useful prognostic biomarker in many other cancers, including renal clear cell, leukemia, gastric cancer, and hepatocellular carcinoma." (PMID 41409683, 2025). "This study demonstrated that STC1-overexpressing human metastasis hepatocellular carcinoma cells (MHCC97L/S1) suppressed the migratory activity of the human monocytic cells (THP-1) and induced the cells towards M1 differentiation." (PMID 33156861, 2020). "Using clinicopathological data, we previously reported that a greater expression of STC1 in hepatocellular carcinoma (HCC) was significantly correlated with smaller tumor size." (PMID 29467934, 2018). "STC1 overexpression was established in the metastatic human hepatocellular carcinoma (MHCC-97L) using lentivirus approach." (PMID 29467934, 2018). "Hepatocellular carcinoma (HCC) an exemplified model of inflammation-related cancer, represents a paradigm of studying the association between STC1 and tumor development." (PMID 26469082, 2015). "Additionally, using siRNASTC1 interference, this study investigated the effect of downregulation of STC1 gene in macrophages on the migration of hepatocellular carcinoma cells Hep3B." (PMID 39654892, 2024). "In hepatocellular carcinoma, the upregulation of STC1 resulted in decreased energy metabolism." (PMID 35607443, 2022). "Mutations in genes such as CHRDL2, STC1, CTGF, GDNF, and FGF7; which are involved in liver fibrosis and inflammation were highlighted, shedding light on their potential role in advancing MASLD towards more severe stages, including liver cirrhosis and hepatocellular carcinoma (HCC)." (PMID 39927143, 2025). "In this study, the co-culture of the human metastatic hepatocellular carcinoma cell line (MHCC97L) stably transfected with a control vector (MHCC97L/P), or STC1-overexpressing vector (MHCC97L/S1) with human leukemia monocytic cell line (THP-1) was conducted." (PMID 33156861, 2020). "The results showed that the decrease of STC1 expression promoted the expression of TBC1 domain family member 3 (TBC1D3), led to the decrease of STAT phosphorylation level, and further inhibited the proliferation and migration of hepatocellular carcinoma in vitro." (PMID 39654892, 2024).
lung carcinoma (17 papers, 2014 to 2025). "STC1 reversely correlates with checkpoint therapy efficacy in patients with melanoma and lung cancer and is associated with poor patient survival across multiple cancer types." (PMID 36795484, 2023). "We observed a reduced expression of STC1, that encodes stanniocalcin 1, a protein reported to functionally participate in the development of some cancers, including lung cancer." (PMID 32635498, 2020). "The same regulatory mechanism was also found in human lung cancer; STC1 promoted the EMT process in cancer cells." (PMID 41020346, 2025). "(iii) STC1 is overexpressed in most lung cancer cell lines and contributes to lung cancer cell growth." (PMID 36499099, 2022). "STC1 can enhance glucose metabolism, ATP production, and lactic acid production of lung cancer cells under normoxic and hypoxic conditions, thus achieving anti-apoptotic properties." (PMID 35692818, 2022). "It is noteworthy that STC‐1 concentration in plasma was significantly higher in lung cancer patients than in healthy volunteers." (PMID 33826244, 2021). "Recent studies targeting STC1 with a vector expressing a suicide gene under a STC promoter inhibited and arrested cell growth in lung cancer cell lines although further research is still required before its potential clinical use." (PMID 34867818, 2021). "Some issues that have been raised to date must be overcome before application of STC‐1 as a new molecular target of lung cancer." (PMID 33826244, 2021). "In this study, we first confirmed STC‐1 expression in plasma samples and tissue slides from lung cancer patients." (PMID 33826244, 2021). "Previous studies have indicated that stanniocalcin‐1 (STC‐1), a hormone involved in calcium and phosphate homeostasis, positively regulates proliferation, apoptosis resistance, and glucose metabolism in lung cancer cell lines." (PMID 33826244, 2021). "In this study, we observed that sera collected from lung cancer patients contained higher level of stanniocalcin‐1 (STC‐1), a hormone maintaining mineral homeostasis, than those from healthy donors." (PMID 33826244, 2021). "We confirmed that STC‐1 levels in peripheral blood were higher in lung cancer patients than in healthy donors and that STC‐1 expression was observed in five out of eight lung cancer cell lines." (PMID 33826244, 2021). "From these results, we inferred that the targeting of STC‐1‐expressing lung cancer cells was sufficient to obtain efficient growth‐arresting effects of tumors." (PMID 33826244, 2021). "We confirmed the expression of STC‐1 in specimens from patients diagnosed as having lung cancer, especially squamous cell carcinoma and adenocarcinoma." (PMID 33826244, 2021). "In this study, we confirmed that STC‐1 was detected in tissue specimens and peripheral blood samples from lung cancer patients." (PMID 33826244, 2021). "Similarly, co-culture with lung cancer cells prompts MSCs to secrete stanniocalcin-1 (STC1), enhancing the survival of lung cancer cells by shifting their metabolism from oxidative phosphorylation to a more glycolytic state." (PMID 40676710, 2025). "MSCs could be activated to reduce apoptosis in UV-irradiated fibroblasts and lung cancer epithelial cells, which may be explained in part by the upregulation and secretion of stanniocalcin-1 (STC-1)." (PMID 37711624, 2023). "Lung cancer patients with high STC1 mRNA expression in tumor tissues had significantly worse overall survival and disease-free survival, as compared to those with low STC1 levels (HR = 1.4, p < 0.001 and HR = 1.5, p = 0.0014, respectively)." (PMID 36499099, 2022). "Notably, a recent study reported that most lung cancer cell lines overexpressed STC1, and inhibition of STC1 significantly reduced cancer cell growth." (PMID 36499099, 2022). "In this study, we investigated if targeting STC‐1 in tumor cells could be a promising strategy for lung cancer gene therapy." (PMID 33826244, 2021).
lung carcinoma (continued). "This study investigated the possibility of using STC‐1 as a new molecular target for lung cancer." (PMID 33826244, 2021). "Although it remains unclear if STC‐1 is involved in the progression of lung cancer through NFIC, it is apparently worthy of further investigation in future studies." (PMID 33826244, 2021). "This study elucidated that STC‐1 could be useful as both a molecular target and as a marker for lung cancer." (PMID 33826244, 2021). "For the last study, we validated whether targeting of STC‐1‐positive lung cancer cells by 5‐FU can also exert growth‐arresting effects against adjacent STC‐1‐negative lung cancer cells." (PMID 33826244, 2021). "Although it was uncertain if targeted STC‐1‐positive lung cancer cells damaged adjacent non‐tumor cells from our study, our results might also represent a promising strategy to target the tumor microenvironment." (PMID 33826244, 2021). "In addition, we showed that effective anti‐tumor effect was obtained by targeting lung cancer cells which express STC‐1." (PMID 33826244, 2021). "First, we sought to clarify the usefulness of STC‐1 as a molecular target for lung cancer therapy." (PMID 33826244, 2021). "The aberrant expression of STC1 has been reported to impact various types of cancer, such as triggering tumor angiogenesis by upregulating the expression of VEGF in gastric cancer cells, causing tumorigenesis and poor clinical outcomes in ovarian, colorectal, and lung cancers." (PMID 36779699, 2023). "Therefore, it would be meaningful to evaluate the possibility of STC‐1 further as a molecular target of lung cancer and to clarify whether STC‐1 expression correlates with tumor malignancy and poor prognosis." (PMID 33826244, 2021). "In vitro examination revealed that paracrine effects of BM-MSC-secreted stanniocalcin-1 (STC1) mediate anti-apoptotic effects in both UV-irradiated fibroblasts and hypoxia-induced injury of lung cancer epithelial cells." (PMID 35741711, 2022). "Based on our previous and present studies on eATP in EMT, STC1, and studies performed by others, we propose a hypothetical model for how eATP and STC1 work to induce EMT and CSC in lung cancer cells." (PMID 36499099, 2022). "We further evaluated whether targeting of STC‐1‐expressing lung cancer cells would influence adjacent STC‐1‐negative cells, or not." (PMID 33826244, 2021).